MMP9 (matrix metallopeptidase 9)
Diseases named in the same sentence as MMP9 in open-access papers (continued):
Sharing a sentence is not in itself a finding about the gene and the disease.
tumor (continued). "Similarly, tumor markers such as matrix metalloproteinase-9 (MMP9), stromal cell-derived factor-1α (SDF-1α), and carcinoembryonic antigen (CEA) are essential indicators of tumor progression and response to treatment." (PMID 40821654, 2025). "To further investigate the role of MMPs in the process of tumor invasion and dissemination, we investigated GA, a naturally occurring plant phenol with known anti-tumor properties, including the inhibition of MMP-2 and MMP-9 activity." (PMID 40869275, 2025). "At the same time, tumor-specific co-regulators can invert this effect: in ER-positive breast-cancer models, E2 induces MMP-9 via PELP1 to PI3K/Akt non-genomic signaling, underscoring tissue- and cofactor-dependent directionality." (PMID 41304763, 2025). "FOXOs contribute to the maintenance of tumor stem cells, mediate drug resistance through the upregulation of the MDR1 protein, and enhance tumor invasiveness by increasing the expression of matrix metalloproteinases (MMP-9 and MMP-13)." (PMID 40424719, 2025). "Hence, this study chose to assess serum concentrations of TNF‐α, IL‐2, IL‐10, MMP‐9, and VEGF‐C to reflect the conditions of the tumor microenvironment before metastasis." (PMID 40808216, 2025). "Furthermore, the ability of CUR to inhibit MMP-9 and upregulate the tissue inhibitor of metalloproteinases-2 (TIMP-2) significantly suppresses tumor angiogenesis, metastasis, and cell proliferation, thereby complementing the antitumor mechanisms of PTX." (PMID 40871063, 2025). "In the process of acquiring the M2 phenotype, GAMs secrete immunomodulatory and tumor-promoting factors such as TGF-β, epidermal growth factor (EGF), IL-10, and the proteolytic enzymes MMP-2 and MMP-9, thereby reinforcing an immunosuppressive tumor milieu within the glioblastoma microenvironment." (PMID 41479886, 2025). "In the MMP-9- and glutathione-rich tumor microenvironment, the MMP-9-mediated degradation of the peptides released chemotherapeutic drugs, enhancing dendritic cell activation, T cell expansion, and inhibiting tumor growth." (PMID 40284474, 2025). "Moreover, N-cadherin increases the sensitivity of tumor cells to fibroblast growth factor 2 (FGF-2), which further enhances the expression of matrix metalloproteinase 9 (MMP-9)." (PMID 41181711, 2025). "In addition, PMN-MDSCs promote tumour progression by secreting VEGF to stimulate angiogenesis, releasing MMP-9 to remodel the extracellular matrix (ECM) and facilitate invasion, and contributing to the establishment of pre-metastatic niches in distant organs." (PMID 41451221, 2025). "Understanding how new Ru(II) complexes interact with ACHE and MMP-9 is crucial, as both enzymes are instrumental in cancer progression, ACHE through its role in cell signaling and proliferation, and MMP-9 in facilitating tumor invasion and metastasis." (PMID 40149886, 2025). "The tumor volume of the tumor-bearing mice decreased, and the concentration of multiple molecules in the peripheral blood of the mice, including HIF-1α, TNF-α, VEGF, and MMP-9, was reduced." (PMID 40563539, 2025). "CD44, MMP-2, MMP-9, N-cadherin, and ZEB-2 were selected because they complementarily represent the three main axes of early tumor invasion: cell adhesion (CD44 and N-cadherin), extracellular matrix degradation (MMP-2 and MMP-9), and epithelial–mesenchymal transition (N-cadherin)." (PMID 40940940, 2025). "Additionally, MMP9 downregulates COL4A1, further promoting ECM degradation and tumour dissemination." (PMID 40806577, 2025). "MMP9, a key member of the matrix metalloproteinase family, promotes tumor invasion and metastasis by degrading the ECM and basement membrane, thereby creating pathways for tumor cell migration and supporting angiogenesis." (PMID 41179295, 2025). "We speculated that LINC01016 may increase the expression of MMP9 through EIF4A3 and played a tumor-promoting role." (PMID 39881131, 2025).
tumor (continued). "It has been demonstrated that phosphorylated STAT3 (p-STAT3), which was significantly decreased by MAE, downregulates important pro-metastatic factors like matrix metalloproteinase-9 (MMP-9), which was significantly decreased, effectively inhibiting tumor growth." (PMID 40943427, 2025). "In addition, STAT3 contributes to tumor cell invasion by upregulating matrix-degrading enzymes such as MMP-2 and MMP-9." (PMID 40723906, 2025). "Principally, TAMs promote tumor cell invasion and dissemination, and through their ability to release cytokines and factors that support growth and ECM-shaping (MMP-2, MMP-9), milk fat globule-EGF factor 8 (MFGE8), IL-6 are correlated with tumor progression and metastasis." (PMID 39981232, 2025). "The F. nucleatum group can stimulate the secretion of MMP-9 and MMP-13 from epithelial cells, leading to the degradation of collagen IV in the basement membrane and extracellular matrix which facilitates tumor progression, including invasion, metastasis, growth, and angiogenesis in the esophagus." (PMID 41471188, 2025). "In particular, to enable tumor-specificdrug release, BrP was covalently bound to TPP+, and thisconjugate was attached to the surface of the nanofibers via a matrixmetalloproteinase-9 (MMP-9)-responsive linker." (PMID 41124053, 2025). "Similarly, quinic acid and its derivatives have shown pro-apoptotic and anti-angiogenic properties in other tumor models by modulating MAPK signaling and reducing MMP-9 expression." (PMID 40872589, 2025). "M2 TAMs promote tumor progression by expressing PD-L1, remodeling the extracellular matrix through matrix metalloproteinases (MMP2, MMP9), enhancing angiogenesis via vascular endothelial growth factor (VEGF), and recruiting immunosuppressive cells such as Tregs." (PMID 40475782, 2025). "By inhibiting TNF-induced MMP9 expression, GOS can hinder tumor spread." (PMID 40002373, 2025). "Additionally, CD133 activation initiates the MAPK pathway, increasing MMP-2, MMP-9, and VEGF expression, thereby promoting angiogenesis and tumor development." (PMID 40399946, 2025). "Advances in nanoparticle, liposomal, and hydrogel-based formulations now enable targeted or sustained delivery of MMP-9 modulators—ranging from tetracyclines and TIMP-mimetics to small-molecule zinc chelators—directly to inflamed, fibrotic, or tumor tissues while minimizing systemic toxicity." (PMID 41304763, 2025). "To further explore the molecular mechanisms underlying these observations, we examined the expression of key extracellular matrix (ECM)-degrading enzymes, matrix metalloproteinase (MMPs), particularly MMP9 and MMP13, which are crucial mediators of tumor invasion and metastasis." (PMID 40332124, 2025). "In later stages of tumor development, neutrophils increase angiogenesis, which in turn leads to tumor progression and local invasion by altering the ECM, releasing VEGF, and manufacturing MMP9." (PMID 40230883, 2025). "The therapeutic potential of targeting MMP9, SPARC, and ITGA5 is heightened when considered in combination, as they are involved in different but complementary pathways of ECM remodelling, fibrosis, and tumor progression." (PMID 39865173, 2025). "MMP-9 had the ability to degrade components of the extracellular matrix (ECM) and release membrane-bound growth factors to establish a microenvironment conducive to tumor formation." (PMID 41445740, 2025). "In addition, matrix metalloproteinases (MMP-2, MMP-9, and MT1-MMP) have been identified in papillary myxomas, contributing to ECM degradation, tumor fragility, and inflammation-driven remodeling." (PMID 41376733, 2025). "For instance, MMP-7 and MMP-9 have been shown to influence the availability of cytokines like interleukin-6 (IL-6) and tumor necrosis factor-alpha (TNF-α), modulating inflammatory signaling and dampening immune cell responses in the tumor microenvironment." (PMID 40265458, 2025).
tumor (continued). "Similarly, endogenous IFN-β has been reported to suppress tumor angiogenesis by downregulating pro-angiogenic factors such as VEGF and MMP9, as well as homing factors in neutrophils." (PMID 39900908, 2025). "Furthermore, immunohistochemical analysis of tumor tissues showed that the number of Ki67-positive cells and the expression of MMP-9 in the LA/DOX NP group were both decreased, confirming that LA/DOX NPs promoted apoptosis of tumor cells." (PMID 41346414, 2025). "MMP-2 and MMP-9 degrade key ECM components—such as collagen IV, laminin, and fibronectin—facilitating basement membrane disruption, increased matrix porosity, and enhanced tumor invasion." (PMID 40906383, 2025). "We show that the primary tumor released elevated levels of EMMPRIN in mice implanted with paternal D2A1 cells (D2A1-WT), generating lung PMN by increasing VEGF, MMP-9 and TGFβ secretion, enhancing angiogenesis, activating fibroblasts, increasing neutrophils infiltration, and remodeling the ECM." (PMID 40370456, 2025). "Moreover, studies have shown that MDSCs can secrete matrix metalloprotein (MMP), and MMP-9 can increase the bioavailability of VEGF and promote the growth and maintenance of tumor blood vessels." (PMID 40131539, 2025). "Similar effects on tumor angiogenesis have been observed with luteolin, as it reduces phosphorylated VEGFR2 induced by VEGF-A and inhibits subsequent proteins including mTOR, AKT, P70S6K, ERK, MMP-2, and MMP-9." (PMID 38611849, 2024). "Finally, we observed that MMP9 secreted by macrophages hydrolyzed MICA, leading to the release of sMICA and promoting immune evasion by the tumor." (PMID 38254761, 2024). "Interestingly, IFN-β inhibits the infiltration of proangiogenic neutrophils that express VEGF, MMP-9, and CXCR4 and reduces tumor growth, suggesting a potential therapeutic approach for targeting neutrophil-mediated tumor angiogenesis." (PMID 38580870, 2024). "The evaluation of the effectiveness of the studied compounds was based on their cytotoxicity, effect on the cell cycle, as well as the expression of key genes of the Hh signaling pathway (Ptch1, Smo, Gli1) and putative target genes of molecules involved in tumor progression: MMP-2 and MMP-9." (PMID 39274874, 2024). "The tumor cells invading the surrounding tissue in SW480 and HT-29 xenografts were evaluated by morphological features using H&E staining and the expression of matrix metaloprotease-2 and -9 (MMP2 and MMP9) on the tumor slices." (PMID 38256960, 2024). "Given the crucial role of MMP-2 and MMP-9 in tumor migration and invasion, research has substantiated that inhibiting the MAPK (JNK/P38/ERK) pathway and reducing MMP-2, MMP-9, and uPA protein expression can effectively prevent cancer cell migration and invasion." (PMID 38374934, 2024). "Additionally, it regulated matrix metalloproteinases MMP-2, MMP-9, and MMP-14, and upregulation of these resulted in collagen degradation and tumor invasion." (PMID 39280415, 2024). "Furthermore, by producing matrix metalloproteinase-9 (MMP-9), MDSCs remodel the extracellular matrix (ECM), which promotes angiogenesis, tumor aggression, and spread." (PMID 38622705, 2024). "For example, the highly expressed TPX2 in HCC might promote tumor cell invasion via activating AKT signaling and subsequently increasing MMP2 and MMP9 expression." (PMID 39458959, 2024). "MMP-9, furthermore, has the ability to activate key growth factors, including transforming growth factor β (TGF-β), VEGF, and tumor necrosis factor α (TNF-α), thereby promoting tumor growth and angiogenesis." (PMID 39769318, 2024). "Notably, HCC patients with high CSC levels exhibited an accumulation of SPP1+ macrophages (Macro_SPP1) expressing metalloproteinases (MMP9, MMP12, and MMP7) regulated by HIF1A, suggesting a hypoxic tumor region connecting Macro_SPP1 and CSC." (PMID 38521868, 2024).
tumor (continued). "MMP-9 locally amplifies the protumourigenic effects of TGF-β, and activated TGF-β directly promotes tumour invasion and angiogenesis, and exerts extensive immunosuppression on the tumour microenvironment, further inducing tumour metastasis." (PMID 38912060, 2024). "Macrophage-derived exosomes overexpressed MMP9 and MMP14 could degrade tumor collagens, further enhancing CD8+ T cells infiltration and the deep delivery of anti-PD-1 antibody to exert anti-tumor effects." (PMID 38644492, 2024). "Moreover, both TAMs and tumor cells secrete VEGF-A, VEGF-C, and MMP-9, which contribute to perineural lymphangiogenesis, further promoting tumor progression." (PMID 39404428, 2024). "Our findings suggest that the alteration of MMP-14 and MMP-9 levels by regorafenib may affect ECM degradation and angiogenesis, thereby suppressing tumor progression." (PMID 39199626, 2024). "Moreover, CTSK activates pre-MMP-9 to generate MMP-9 under acidic conditions, promoting tumour cell migration and metastasis." (PMID 38594611, 2024). "In a study on tumor disease, it was also found that IL-33 may activate the ST2-NF-κB signaling pathway, increasing the expression of MMP-2 and MMP-9." (PMID 39172956, 2024). "Tumor tissue staining demonstrated a significant reduction in neutrophils and ICAM1 within the tumors, accompanied by inhibited expression of the MAPK pathway and its downstream target MMP9." (PMID 38907234, 2024). "Up-regulated the expression of IL-8, MMP2, MMP9, p-STAT3, and ZEB1 in tumor." (PMID 39906741, 2024). "After that, we analyzed the protein expression levels of CDH5, MMP9 and MAPK1 in normal kidney tissues and ccRCC by CPTAC database, MMP13 for included in CPTAC database, and the protein expression levels of CDH5, MMP9 and MAPK1 were significantly higher than that in normal tissues in tumor tissues." (PMID 38580922, 2024). "Another study found that Per1 knockout increased the expression of MMP9 and MMP2 and also reduced the expression of TIMP-2, which may lead to the observed increase in tumor cell invasion and migration." (PMID 38903177, 2024). "The addition of IL-1RA during co-culture significantly inhibited the activation of both MMP-2 and MMP-9 in SUM159 cells and suppressed MMP-2 activity in MCF12A cells These results underscore the role of IL-1β signaling in promoting tumor cell invasiveness and MMP activation in TNBC." (PMID 39801513, 2024). "In preclinical models of CRC, neutrophil-secreted MMP-9 was also shown to activate TGF-β−mediated T cell suppression and tumor promotion, suggesting that targeting either TGF-β receptor or MMP-2/9 inhibitors could be a potential therapeutic strategy." (PMID 39795864, 2024). "The identification of potential markers such as MMP9 and TWIST1 in metastatic tumor cells may offer opportunities for early detection and targeted therapies for aggressive cancers." (PMID 38252369, 2024). "The present study found significant increases in MMP-9 expression in mRNA and protein, the primary role of which is to degrade the extracellular matrix and enhance MDSC accumulation in the tumor tissues of groups with enhanced tumor growth." (PMID 39119610, 2024). "However, in tumour-derived MSCs, only CCN2 inhibited cancer cell proliferation, mobility and invasion, and it decreased the levels of MMP-9, MMP-2 and epithelial-mesenchymal transition markers in vitro." (PMID 39120301, 2024). "Conversely, ANGPTL4 inhibition significantly repressed the tumor weight and volume of SKOV3 cells with low vimentin, PCNA, MMP9, ESM1 and CD34 expression in comparison with the vector and NC groups, which could also be rescued by Colivelin." (PMID 38212795, 2024). "ANGPTL4 overexpression could promote OC cell growth (tumor weight and volume) with higher expression of vimentin, proliferating cell nuclear antigen (PCNA), MMP9, ESM1 and CD34, which could be rescued by AG490." (PMID 38212795, 2024).
tumor (continued). "Moreover, CAFs contribute to tumor proliferation by secreting matrix-metalloproteinases (MMPs), including MMP-2, MMP-3, MMP-9, and MMP-13." (PMID 39338413, 2024). "Interestingly, we found that both MMP9 and FMOD were upregulated in LK0902 and LK0923 cells when cultured with unmatched CAFs compared to when cultured with tumor-matched CAFs." (PMID 38822309, 2024). "Finally, we observed that MMP9 secreted by macrophages hydrolyzed MICA, leading to the release of sMICA and promoted immune evasion by the tumor." (PMID 38254761, 2024). "Additional studies showed tumor-infiltrated neutrophils produced proangiogenic factors including VEGF and MMP9 in response to IFNβ in mouse melanoma and fibrosarcoma models or could induce tumor cells to elevate VEGF expression." (PMID 38786066, 2024). "Further research has found that EA can increase the expression level of tissue inhibitors of metalloproteinases (TIMP-1), downregulate the expression of MMP-9, reduce the MMP-9/TIMP-1 ratio, and protect the integrity of the extracellular matrix (ECM), thereby inhibiting tumor metastasis." (PMID 38803433, 2024). "In addition, PSMA also plays a role in the degradation of the extracellular matrix (ECM) by regulating matrix metalloproteinases, such as MMP7 and MMP9, increasing ECM breakdown and promoting tumor invasion." (PMID 39272896, 2024). "Higher levels of MMP‐9 mRNA and protein have been observed in PAs compared to healthy tissues, where it facilitates the cleavage of MICA into soluble MICA, ultimately promoting tumor immune escape." (PMID 39688352, 2024). "Concerning tumor progression, the steroid sapogenin diosgenin reduced the migration and invasion capabilities of PC3 cells, inhibiting the expression and activation of MMP-2, MMP-7, and MMP-9, which have a crucial role in extracellular matrix degradation." (PMID 39200101, 2024). "Furthermore, MDSCs can secrete MMP9 to regulate the function of VEGF to promote angiogenesis and tumor cell extravasation and migration." (PMID 38571500, 2024). "They further advocated that this effect may be mediated by the prevention of the accumulation of tumor-infiltrating T cells in the tumor microenvironment (TME) and/or increased expression of matrix metalloproteinase-9 (MMP-9)." (PMID 38667331, 2024). "Expression analysis showed that MMP3, MMP9, TIMP1 and VEGFA were upregulated in tumor samples." (PMID 39177661, 2024). "Suppression of fibronectin, vimentin, N-cadherin, MMP-9, MMP-2, twist, and snail.↑ Epithelial markers E-cadherin and Occludin levels.↓ Migratory and invasive potential of tumor cells by reversing epithelial-to-mesenchymal transition (EMT). ↓ PI3K/Akt/mTOR activation." (PMID 38611719, 2024). "At the same time, the decrease in MMP-2, MMP-9 SNAI1 and TWIST1 protein levels in IL-22 + LY294002 cells indicated that inhibition of the PI3K/AKT signaling pathway reduced MMP expression, attenuating tumor cell invasion and metastasis." (PMID 39073546, 2024). "TAMs respond to hypoxic conditions within tumor tissue by secreting various factors, including VEGFs, basic fibroblast growth factor (bFGF), thymidine phosphorylase, and multiple matrix metalloproteinases (MMPs), such as MMP-2, MMP-7, MMP-9, and MMP-12." (PMID 39404428, 2024). "The results of gene expression analysis demonstrated a slight decrease in the expression of MMP-9 and an increase in the expression of TIMP-1 in tumorous samples compared to normal adjacent tissues, which correlates with an increase in the expression of these proteins." (PMID 39062015, 2024). "Although immunosuppressive CD163+ M2 macrophages and MMP9+ cells were detected, these cells were predominantly located around the remaining tumor cells rather than infiltrating the tumor like cytotoxic T cells." (PMID 39407789, 2024). "Additionally, the unmatched CAFs significantly upregulated the mRNA expression of MMP1, MMP9 and FMOD in tumor cells compared to tumor-matched CAFs." (PMID 38822309, 2024).